VEGFD (vascular endothelial growth factor D)
Description:
Growth factor active in angiogenesis, lymphangiogenesis and endothelial cell growth, stimulating their proliferation and migration and also has effects on the permeability of blood vessels. May function in the formation of the venous and lymphatic vascular systems during embryogenesis, and also in the maintenance of differentiated lymphatic endothelium in adults. Binds and activates VEGFR-2 (KDR/FLK1) and VEGFR-3 (FLT4) receptors.
Synonyms: VEGF-D; FIGF
Tractability: Antibody: its Gene Ontology location is reachable by antibodies, with high confidence; UniProt places it where antibodies can reach, with medium confidence; UniProt predicts a signal peptide or a membrane-spanning region.
Gene: Protein-coding gene on chromosome X (15,345,594 to 15,384,509, reverse strand). Ensembl gene ENSG00000165197.
Subcellular location: Secreted
Pathways (Reactome):
Signal Transduction: VEGF binds to VEGFR leading to receptor dimerization; VEGF ligand-receptor interactions
Hemostasis: Platelet degranulation
Gene Ontology:
Molecular function: chemoattractant activity; protein binding; vascular endothelial growth factor receptor binding; growth factor activity; platelet-derived growth factor receptor binding; identical protein binding; receptor ligand activity; vascular endothelial growth factor receptor 3 binding
Biological process: induction of positive chemotaxis; positive regulation of mast cell chemotaxis; positive regulation of cell population proliferation; response to hypoxia; sprouting angiogenesis; vascular endothelial growth factor receptor signaling pathway; vascular endothelial growth factor signaling pathway; dopaminergic neuron differentiation; positive chemotaxis
Cellular component: extracellular region; platelet alpha granule lumen; membrane
Homologues: Orthologues: chimpanzee VEGFD (99% identical), macaque VEGFD (97% identical), rabbit VEGFD (88% identical), dog VEGFD (88% identical), mouse Vegfd (85% identical), pig VEGFD (84% identical), guinea pig VEGFD (81% identical), rat Vegfd (77% identical), tropical clawed frog vegfd (55% identical), zebrafish vegfd (33% identical). Paralogues in human: VEGFC (39% identical), VEGFA (16% identical), PGF (14% identical), VEGFB (10% identical).
Diseases named in the same sentence as VEGFD in open-access papers:
VEGFD is named in the same sentence as 210 diseases in open-access papers, as found by Europe PMC text mining. Sharing a sentence is not in itself a finding about the gene and the disease. The quoted sentences say what the papers report.
breast carcinoma (43 papers, 2005 to 2025). "The expression of VEGFC was significantly higher than that of VEGFD in patients with breast cancer, as revealed by investigating TCGA database (p < 0.0001)." (PMID 35600335, 2022). "However, interleukin 7 was found to upregulate vascular endothelial growth factor D (VEGF-D) in breast cancer cells and induce lymph angiogenesis in vivo." (PMID 37217704, 2023). "Besides FGF13 and VEGFD, the candidate CTAG2 is involved in cellular movement and has previously been associated with invasion in breast cancer." (PMID 30555413, 2018). "Based on GeoMx DSP spatial multi‐omics analysis, it was identified that VEGFD and PAK1 expression levels were markedly increased in breast cancer cells co‐cultured with F. nucleatum." (PMID 40070022, 2025). "In breast cancer, a recent study demonstrated that minor subclones expressing IL11 and FIGF (or VEGFD) indirectly cooperate to promote metastatic progression by modulating bone-marrow-derived mesenchymal stromal cells." (PMID 38506114, 2024). "In breast cancer, there is a positive correlation between SOX18 and vascular endothelial growth factor D (VEGF-D), suggesting that SOX18 positively influences angiogenesis." (PMID 38132479, 2023). "Kaplan–Meier survival analysis and log-rank tests were used to determine the prognostic significance of expression of the three genes, VEGFD, TSLP, and PKMYT1, in patients with breast cancer." (PMID 35472078, 2022). "Accordingly, three consistently relevant genes (i.e., VEGFD, TSLP, and PKMYT1) were selected for the diagnosis of breast cancer." (PMID 35472078, 2022). "We hypothesized that VEGFD and PAK1 may play pivotal roles in the F. nucleatum‐promoted proliferation and migration of breast cancer cells." (PMID 40070022, 2025). "In addition, three stable relevant genes, namely VEGFD, TSLP, and PKMYT1, were chosen for the diagnosis of breast cancer." (PMID 35472078, 2022). "A study demonstrated that primary breast tumours induce sentinel lymph node lymphangiogenesis and that tumour-derived VEGFC plays an important role in their lymphangiogenesis in breast cancer, but not VEGFD." (PMID 35600335, 2022). "Moreover, we show that expression of both miR526b and miR655 is positively correlated with expression of angiogenesis (CD31 and VEGFA) and lymphangiogenesis markers (VEGFC, VEGFD, and LYVE1) in human breast cancer tissue." (PMID 31277414, 2019). "In addition, survival analysis showed that VEGFD and TSLP could be used to predict the prognosis of patients with breast cancer." (PMID 35472078, 2022). "Therefore, VEGFD and TSLP could be used to predict prognosis in patients with breast cancer, whereas PKMYT1 is not suitable for this purpose." (PMID 35472078, 2022).
lymph node metastasis (37 papers, 2003 to 2024). "Vascular endothelial growth factor-D expression was shown to be associated with lymph node metastasis, although an inverse correlation with lymphatic invasion and the number of nodal metastases was described." (PMID 16189523, 2005). "The overexpression of the lymphangiogenic factors VEGFC and VEGFD, activators of VEGFR3, has been associated with lymph node metastasis and poor outcome in BC patients." (PMID 36835014, 2023). "Vascular endothelial growth factor D (VEGF-D) is a key lymphangiogenic factor that is associated with lymphangiogenesis and lymph node metastasis in GBC." (PMID 26992854, 2016). "Furthermore, we determined that vascular endothelial growth factor D (VEGF-D), another key lymphangiogenic factor similar to VEGF-C, is associated with lymphangiogenesis and lymph node metastasis of GBC." (PMID 26992854, 2016).
gastric cancer (26 papers, 2003 to 2024). A primary or metastatic malignant neoplasm involving the stomach. "For example, lncRNA CRART16 promotes gastric cancer angiogenesis by sponging miR-122-5p to upregulate FOS/VEGFD expression, and is a prognostic marker and therapeutic target for gastric cancer." (PMID 39198393, 2024). "Our study demonstrates that CRART16 promotes angiogenesis and tumor proliferation in gastric cancer by acting as a miR-122-5p sponge and thereby upregulating c-Fos and VEGFD expression." (PMID 35537818, 2022). "Several studies have proved that VEGFD contributes to the angiogenesis of gastric cancer, and VEGFD is a biomarker of disseminated disease in gastric cancer patients." (PMID 35537818, 2022). "Besides, the sequencing data showed that FOS and VEGFD expression were upregulated in CRART16-overexpressing gastric cancer cells." (PMID 35537818, 2022). "Compared with negative control cells, ELISA results demonstrated that VEGFD expression was upregulated in conditioned media from CRART16- overexpressing gastric cancer cells (**P < 0.01)." (PMID 35537818, 2022). "Compared with the negative control cells, CRART16-overexpressing gastric cancer cells expressed a lower level of miR-122-5p and higher FOS and VEGFD (*P < 0.05)." (PMID 35537818, 2022).
lung carcinoma (26 papers, 2007 to 2025). "SDF4 interacts with CXCR4 to trigger VEGFD expression in endothelial cells and promotes the angiogenesis of lung cancer." (PMID 36606322, 2023). "The H&E and immunohistochemistry (IHC) results of the lung tissue section showed that VEGFD protein was significantly low expressed in the lung cancer mice model." (PMID 35941690, 2022). "In turn, the Xq22 region harbors several putative tumors suppressor genes which are inactivated by mutations in lung cancer cell lines and primary tumors (i.e. GRPR, VEGFD,and MID1)." (PMID 25415227, 2015). "Likely, it was shown that c-Fos and c-Jun dimer promotes the interleukin-7-induced lymphangiogenesis in lung cancer by upregulating VEGFD expression." (PMID 25260594, 2014). "We speculate that the dual action of VEGFD in lung cancer represses tumorigenesis of LUAD, which is our next research scope." (PMID 35941690, 2022). "Hu and colleagues showed that deguelin could inhibit the growth and lymphatic metastasis of human lung cancer through suppression of VEGFD pathway." (PMID 29416603, 2018). "We explored the expression of the VEGFA, VEGFC, and VEGFD proteins in lung cancer and adjacent tissues and showed that VEGFA, VEGFC, and VEGFD were substantially highly expressed in lung cancer tissues, which may be the main source of VEGF-related protein expression in TDLNs." (PMID 40693467, 2025).
lymphangioleiomyomatosis (23 papers, 2013 to 2026). A multifocal neoplasm with perivascular epithelioid cell differentiation affecting almost exclusively females of child-bearing age. "Background/Objectives: Lymphangioleiomyomatosis (LAM) is a rare cystic lung disease for which serum vascular endothelial growth factor D (VEGF-D) is a recommended diagnostic biomarker." (PMID 41750682, 2026). "This dysregulation particularly affects the brain and skin, causing epilepsy, neurodevelopmental issues and hypopigmentation, and is linked to elevated vascular endothelial growth factor-D (VEGF-D) levels in conditions like lymphangioleiomyomatosis (LAM) and angiomyolipomas (AMLs)." (PMID 40558831, 2025). "In lymphangioleiomyomatosis (LAM), tuberous sclerosis gene mutations activate the mechanistic target of the rapamycin pathway, resulting in vascular endothelial growth factor-D (VEGF-D) overproduction." (PMID 30818375, 2019). "The abnormal activity of VEGFD might lead to several types of diseases, such as lymphangioleiomyomatosis, pulmonary diseases, and cardiovascular diseases." (PMID 34612148, 2021). "Vascular endothelial growth factor-D (VEGF-D) is the most commonly used biomarker for diagnosing lymphangioleiomyomatosis (LAM)." (PMID 36817769, 2023). "Serum levels of vascular-endothelial growth factor-D (VEGF-D), a marker which, at high levels, is useful for the diagnosis of lymphangioleiomyomatosis, was requested and the result of 125pg/mL, a little above the reference value (31-86pg/mL), ruled out that possibility." (PMID 27178371, 2016). "One was diagnosed with SR-ILD after MDT and one was diagnosed with lymphangioleiomyomatosis (LAM) due to the HRCT pattern and elevated vascular endothelial growth factor D. The final diagnosis in one patient was bland chronic alveolar hemorrhage." (PMID 28326178, 2017).
angiomyolipoma (13 papers, 2011 to 2025). A neoplasm with perivascular epithelioid cell differentiation often associated with tuberous sclerosis. "Two angiomyolipoma (AML) cases presented with bilateral diffuse cystic lesions atypical of LAM, with normal serum vascular endothelial growth factor-D (VEGF-D) levels." (PMID 39934870, 2025).
melanoma (13 papers, 2004 to 2025). A malignant, usually aggressive tumor composed of atypical, neoplastic melanocytes. "In addition, we explored the associations of VEGFD with HEVs and lymphocyte homing in a melanoma model." (PMID 40693467, 2025). "Vascular endothelial growth factor D, another lymphangiogenic growth factor, has also been shown to be upregulated in melanoma and other tumours." (PMID 14760386, 2004). "The results show that, in the VEGFD-OE group, the tumor weight and volume were substantially greater than those in the control group, which indicated that VEGFD could substantially promote melanoma progression." (PMID 40693467, 2025). "The results of the flow cytometry (FCM) assay indicated that the expression of LTβR on the surface of HEVs was lower in the VEGFD-OE group than in the control group, suggesting that VEGFD also induced HEV dedifferentiation in melanoma." (PMID 40693467, 2025). "Intriguingly, RNA‐based analyses (RT–PCR) indicated that melanoma‐driven VEGFD was not altered by BO‐110." (PMID 34762341, 2021).
Obesity (13 papers, 2016 to 2024). Accumulation of substantial excess body fat. "VEGFC and -D are elevated in adipose tissue during obesity and an overexpression of VEGFD in adipose tissue resulted in de novo lymphatics and improved overall metabolism in mice." (PMID 34200994, 2021). "Using Adipo-VD mice, a model of adipocyte-specific, inducible overexpression of the potent lymphangiogenic factor vascular endothelial growth factor-D (VEGF-D), we previously identified that dense de novo adipose lymphatics reduced immune accumulation and improved glucose homeostasis in obesity." (PMID 32390866, 2020).
ovarian carcinoma (13 papers, 2003 to 2025). A malignant neoplasm originating from the surface ovarian epithelium. "Furthermore, in both ovarian cancer cell lines, the reduced expression of VEGFD induced by fucosterol was significantly decreased following additional co-treatment with chemotherapeutic agents compared with control cells." (PMID 32429354, 2020). "Similarly, treatment with fucoidan repressed the mRNA expression of angiogenesis related genes including VEGFA, VEGFB, VEGFC, VEGFD, FLT-1, FLT-4, and KDR in the ovarian cancer cells." (PMID 31936539, 2020).
COVID-19 (11 papers, 2021 to 2024). A disease caused by infection with severe acute respiratory syndrome coronavirus 2. "Recently, VEGFD was proposed as a biomarker for COVID-19 due to growing evidence for its implications in acute respiratory distress syndrome (ARDS) and acute lung injury." (PMID 36405747, 2022).
renal angiomyolipoma (8 papers, 2011 to 2025). "We also collected data on TSC gene mutations and explored the utility of serum vascular endothelial growth factor D (VEGF-D) as a biomarker for TSC associated kidney angiomyolipomas." (PMID 21915260, 2011).
Stroke (7 papers, 2013 to 2025). Sudden impairment of blood flow to a part of the brain due to occlusion or rupture of an artery to the brain. "In mouse models of stroke and retinal degeneration, VEGFD levels decrease significantly, leading to dendritic loss, while VEGFD supplementation preserves dendritic structure and neuronal function." (PMID 40050849, 2025). "Accordingly, nasally delivered VEGFD mimetics mitigate stroke-induced dendrite loss and brain damage in mice." (PMID 34959983, 2021). "Similarly, the nuclear accumulation of Histone Deacetylase 4 (HDAC4), an epigenetic regulator implicated in several neurodegenerative disorders—including stroke, PD, AD, and ataxia telangiectasia—also disrupts dendrite architecture of mature neurons by negatively affecting VEGFD expression." (PMID 40050849, 2025). "VEGFD delivery in a stroke model successfully protected basal dendrites of pyramidal neurons in layer 2/3 of motor cortex from stroke-induced damage." (PMID 40050849, 2025). "Indeed, mouse VEGFD neuronal expression quickly decreased following excitotoxicity in the adult retina or in the cortex after stroke." (PMID 40050849, 2025).
heart failure (6 papers, 2019 to 2024). Inability of the heart to pump blood at an adequate rate to meet tissue metabolic requirements. "to HENRY with BNP and NT-proBNP, the most important biomarkers for heart failure, and vascular endothelial growth factor D (VEGFD), a novel biomarker for left pulmonary hypertension subsequent to left heart disease, can be regarded as general proof of the principles of the present analyses." (PMID 38999939, 2024).
lung adenocarcinoma (6 papers, 2003 to 2022). A carcinoma that arises from the lung and is characterized by the presence of malignant glandular epithelial cells. "Here, we attempt to dissect the role and underlying mechanism of S-nitrosylation-mediated VEGFD suppression in lung adenocarcinoma (LUAD)." (PMID 35941690, 2022). "The TCGA analysis showed that VEGFD mRNA was decreased in multiple cancers, especially lung adenocarcinoma (LUAD)." (PMID 35941690, 2022). "A significant mRNA down-expression of VEGFC and VEGFD has been reported in human lung adenocarcinomas." (PMID 29137669, 2017).
metastatic disease (6 papers, 2012 to 2025). "The results demonstrate that clinico-pathological parameters remain the most significant predictors of cancer specific survival; however, high VEGFR1 or VEGFD can predict poor cancer specific survival on univariate analysis for locally advanced and metastatic disease." (PMID 23577117, 2013). "Since LAM muscle cells express two lymphangiogenic growth factors—vascular endothelial growth factor C (VEGF-C) and vascular endothelial growth factor D (VEGF-D)—and disseminate through the lymphatic system, LAM is considered a low-grade metastatic neoplasm." (PMID 39858105, 2025).
non-small cell lung carcinoma (6 papers, 2010 to 2021). A group of at least three distinct histological types of lung cancer, including non-small cell squamous cell carcinoma, adenocarcinoma, and large cell carcinoma. "A gene signature containing VEGFD plus VEGFA and VEGFB is a prognostic indicator in early-stage non-small cell lung cancer (NSCLC) through detecting multiple gene transcription levels by quantitative polymerase chain reaction." (PMID 34612148, 2021).
breast tumor (5 papers, 2013 to 2022). "IL‐7/IL‐7R signaling was shown to induce lung and breast tumor growth and lymphangiogenesis via upregulation of vascular endothelial growth factor D (VEGF‐D)." (PMID 36054746, 2022). "It is very well known that COX-2 induces angiogenesis and lymphangiogenesis through production of VEGFC and VEGFD, and upregulation of PI3K/Akt signalling and COX-2 overexpression can also induce LYVE-1 over expression in mouse breast tumours." (PMID 31277414, 2019). "The expression of VEGFD in breast tumours was significantly higher than that in the non-adjacent control." (PMID 35600335, 2022).
cystic lung diseases (5 papers, 2012 to 2026). "Serum levels of vascular endothelial growth factor-D (VEGF-D), a ligand for the lymphatic growth-factor receptor VEGFR-3/Flt-4, are higher in most LAM patients than in healthy controls or in patients with other cystic lung diseases (OCLD)." (PMID 36817769, 2023). "Vascular endothelial growth factor-D (VEGF-D), a ligand for the lymphatic growth-factor receptor VEGFR-3/Flt-4, is elevated in serum of patients with LAM compared with healthy volunteers and patients with other cystic lung diseases." (PMID 22513045, 2012).
endometriosis (4 papers, 2020 to 2025). The growth of functional endometrial tissue in anatomic sites outside the uterine body. "Looking at patients with DIE, we found Chemokine ligand 19, Stem cell factor, Vascular endothelial growth factor D, Interleukin-6 receptor alpha and Melanoma inhibitory activity to be increased compared to endometriosis patients without DIE." (PMID 32604857, 2020).
head and neck cancer (4 papers, 2016 to 2023). A primary or metastatic malignant neoplasm affecting the head and neck. "Coherently with this latter evidence, in head and neck cancer, a higher expression of AhRR correlates with a higher production of VEGFD, upregulation of Akt, and subsequent tumor growth." (PMID 37511212, 2023).
Hypertension (4 papers, 2020 to 2024). The presence of chronic increased pressure in the systemic arterial system. "The previous reports also demonstrated that enhancing renal lymphatic expansion by over-expressing VEGFD prevented the development of hypertension." (PMID 33200983, 2020).
Lipedema (4 papers, 2020 to 2023). Disorder of adipose tissue characterized by symmetric and bilateral enlargement of the lower extremities due to abnormal deposition of subcutaneous fat often in obese women. "With regard to other cytokines, the expression level of VEGFR-3 has been found to increase with the decreased expression of vascular endothelial growth factor A (VEGF-A) and vascular endothelial growth factor D (VEGF-D) in the AT of lipedema patients." (PMID 36551837, 2022).